FAP (fibroblast activation protein alpha)
Diseases named in the same sentence as FAP in open-access papers (continued):
Sharing a sentence is not in itself a finding about the gene and the disease.
cancer (continued). "The radiopharmaceutical FAP-2286 was developed for the imaging and treatment of FAP-expressing cancers." (PMID 37086273, 2023). "The current study started with analyzing the mRNA level of FAP in a list of human cancers, where it was found that FAP mRNA was significantly up-regulated in 22 of 31 cancers." (PMID 37325617, 2023). "Preclinical evaluations of 18F-FAPI-04 PET/CT have demonstrated promising results in cancer imaging of FAP expression in mice, proving its safety and feasibility for further clinical translation." (PMID 37542659, 2023). "For example, FAP+ fibroblasts in human breast tumor stroma can greatly increase cancer cell migration and induce epithelial-mesenchymal transition." (PMID 37006278, 2023). "This often leads to overexpression of membrane serine protease fibroblast activating protein alpha (FAP-α, also known as prolyl endopeptidase FAP), which is estimated to be overexpressed in approximately 90% of human cancers." (PMID 36477400, 2023). "We first established CDX models with cancer types that express FAP: HepG2-FAP cells and a mixture of CAFs and PANC1 cells." (PMID 38031188, 2023). "In these case series, FAP-targeted radionuclide therapy has resulted in objective responses in difficult to treat end-stage cancer patients with manageable adverse events." (PMID 36813980, 2023). "In the next step, we found a significant co-expression of FAP and angiogenesis-related genes for most cancer entities from our TCGA dataset and our validation datasets." (PMID 36672341, 2023). "Specifically, myCAF subset is situated in proximity to cancer cell nests and is characterized by elevated expression levels of both FAP+ and ꬰ-SMA." (PMID 38095634, 2023). "FAP has been touted as an attractive treatment target for oncology in brain tumors and other cancers." (PMID 39355017, 2023). "Multiple studies conducted on different types of cancers have revealed a strong correlation between elevated levels of FAP and the presence of cancer." (PMID 37864148, 2023). "In the case of PDAC, FAP is not only overexpressed by CAFs, but also by the cancer cells themselves, indicating a potential autocrine loop between CAFs and cancer cells." (PMID 37345133, 2023). "Given these properties, Gallium-68-labeled fibroblast activation protein inhibitor (68Ga-FAPI) has emerged as a novel FAP-targeting radiotracer for PET cancer imaging, promising in vivo visualization of tumor stroma." (PMID 37542659, 2023). "Previous clinical trials have shown that antibodies specific for FAP have shown safe and effective results in phase I trials in advanced cancer." (PMID 36759842, 2023). "We identified significant changes in metabolism that identify, for the first time, the role of FAP-α in cancer cell metabolism." (PMID 36937451, 2023). "FAP, an essential surface marker of CAFs, performs a critical function in tumorigenesis and acts as an immunosuppressant in the cancer microenvironment." (PMID 37752545, 2023). "Fibroblast activation protein alpha (FAP) has been proposed as a potential target in various cancer types." (PMID 37333052, 2023). "Given the differential expression of FAP, with limited to absent expression in normal tissues and high expression in CAFs, approaches to diagnostically and therapeutically target FAP as a way to indirectly target cancer cells are of great interest." (PMID 37333052, 2023). "In oral squamous cell carcinoma, an in vitro investigation showed that FAP overexpression increases cancer cell proliferation, migration, and invasion through PTEN/PI3K/AKT and Ras-ERK activation and its downstream signaling." (PMID 37316886, 2023). "It is also postulated that FAP TRT is particularly useful in combination with other anti-cancer treatments." (PMID 36813980, 2023). "In adult tissues, activated FAP almost only exists in the stroma of wound healing, fibrosis, and malignant tumors." (PMID 36675506, 2023).
cancer (continued). "Myeloid dendritic cell is another kind of antigen-presenting cells that we found to be positively correlated with FAP expression among various cancers in this research." (PMID 37166418, 2023). "As fibroblasts are highly prevalent within tumors, targeting FAP would be a valuable approach for imaging tumors and for the development of novel radiopharmaceuticals for cancer therapy." (PMID 36674595, 2023). "One approach to utilize FAP in cancer treatment is through radioisotopes-labeled theranostics ligands." (PMID 36864362, 2023). "FAPI, which was created by taking advantage of the cancer specificity of FAP, has been shown to have excellent performance as a PET/CT probe." (PMID 37240044, 2023). "Targeting FAP for cancer treatment has been a field of active research, with several strategies being explored concurrently." (PMID 37251405, 2023). "Surprisingly, we observed that in almost all cancer types, FAP expression was positively correlated with the infiltration of two major antigen-presenting cells, macrophages and myeloid dendritic cells." (PMID 37166418, 2023). "The use of oncolytic viruses or virally related vaccine that preferably proliferate in cancer cells is deemed to be plausible as it will promote cytolysis in cancer cells and induces immune cells to kill FAP positive-CAF." (PMID 37035187, 2023). "FAP-specific CAR-T cells inhibited the growth of FAP-positive human cancer cells in the peritoneal cavity of mice and significantly prolonged the survival of mice." (PMID 38516299, 2023). "Fibroblast activation protein (FAP) is among the most popular targets in nuclear medicine imaging and cancer theranostics." (PMID 38706713, 2023). "The expected results will provide new information on the prognostic value of FAP in GI tumors and thereby support health care professionals and patients in their decision-making, as well as aid in patient selection for multimodal cancer therapy." (PMID 37099374, 2023). "As pan-cancer biomarkers, FAP with radiolabeled FAPI-based molecules (including FAPI-04/46) have yielded encouraging results for PET imaging of cancer." (PMID 37142301, 2023). "For FAP, significantly positive Pearson correlations coefficients for most cancer entities were found with prominent angiogenesis-related genes FLT1 (also known as VEGFR1), KDR (also known as VEGFR2), HIF1A, and ETS1." (PMID 36672341, 2023). "In conclusion, our research reveals novel insights and extracts the potential antitumor values of FAP from a pan-cancer perspective, particularly in the area of immunotherapy." (PMID 37166418, 2023). "FAP is known to be overexpressed in breast, colorectal, pancreatic, lung, bladder, ovarian and other cancers." (PMID 37337635, 2023). "As another well-known biomarker of CAFs, the subset of CAFs with high FAP expression promote cancer cell proliferation, invasion and treatment resistance." (PMID 36759842, 2023). "In recent years, radiolabelled FAP inhibitors (FAPIs) are becoming increasingly important in cancer diagnostics and also for targeted radionuclide therapy." (PMID 37631053, 2023). "Our data demonstrate that (R)-(((quinoline-4-carbonyl)-d-alanyl)pyrrolidin-2-yl)boronic acid is a promising pharmacophore for the design of FAP-targeted radiopharmaceuticals for cancer imaging and radioligand therapy." (PMID 37375746, 2023). "Recently, a radiotracer based on a specific enzymatic inhibitor of FAPα (FAPI) was developed and showed a high specificity for cancer-associated fibroblasts both in murine and human tumors." (PMID 37880678, 2023). "For instance, FAP was found able to promote migration and invasion of cancer cells by binding to ENO1 and activating NF-κB signaling pathway in colorectal adenocarcinoma (COAD)." (PMID 37325617, 2023). "As a significant biomarker of CAFs and an emerging cancer promotor, FAP is deemed one of the most feasible and clinically useful CAF markers." (PMID 37784082, 2023).
cancer (continued). "We successfully synthesized and evaluated two novel 68Ga-labeled (R)-pyrrolidin-2-yl-boronic acid-derived PET tracers for FAP-targeted cancer imaging." (PMID 37375746, 2023). "Regarding clinicopathological features, significant differences were observed in the pathological T stage and area index of αSMA and FAP between the PD-L1± cancer cell groups." (PMID 37668710, 2023). "In histopathological studies, FAP-positive CAFs have been found in more than 90% of epithelial tumors, so FAP has become a therapeutic and imaging target for various malignant tumors." (PMID 36675506, 2023). "Our laboratory is actively exploring the synergistic therapeutic efficacy of FAP TRT with antibody–drug conjugate in stromal-abundant malignant tumors." (PMID 38706713, 2023). "Outside of cancer, FAP-α fibroblasts play a role in preserving tissue homeostasis in skeletal muscle, and FAP-α is expressed by PDGFR-α+, Sca-1+ multipotent bone marrow stromal cells." (PMID 36937451, 2023). "Future studies should investigate changes induced by FAP-α overexpression in CAFs as well as in other cancer cells." (PMID 36937451, 2023). "One marker of CAFs, fibroblast activation protein–α (FAP), was targeted by combining a traditional cancer vaccine with a vaccine that selectively targets FAP+ fibroblasts." (PMID 37180129, 2023). "Fibroblast activation protein (FAP) is highly expressed in the stroma of a variety of human cancers and is therefore considered a promising target structure for diagnostic and therapeutic approaches." (PMID 36769616, 2023). "This therapeutic strategy holds promise for treating MPM and other cancers where FAP is highly expressed." (PMID 38516299, 2023). "Fibroblast activation protein (FAP) activation and inhibition plays a pivotal role in cancer and inflammation." (PMID 37345192, 2023). "We found that all the fibroblast clusters showed a high expression of the well-defined panCAF markers including COL1A1, DCN, VIM, FAP, and PDPN4, indicating the identified fibroblasts are likely cancer-associated fibroblasts (CAFs)." (PMID 37612267, 2023). "As a type II transmembrane serine protease, fibroblast activation protein (FAP) belongs to the dipeptidyl peptidase (DPP) 4 protein family and is highly expressed in the cancer-associated fibroblasts in about 90% of normal human epithelial tumors." (PMID 37057133, 2023). "The heatmap illustrates that most immune-related genes have a significant positive correlation with FAP expression across cancer types, except for DLBC." (PMID 37490719, 2023). "Lastly, due to the current application of FAP inhibitors in cancer treatments, FAPI-PET imaging opens the door to a new theranostic approach to cardiovascular diseases." (PMID 37762974, 2023). "The roll-out of the novel pan-cancer tracer family, fibroblast activation protein (FAP) ligands, has opened a new avenue for the diagnosis of numerous epithelial malignancies." (PMID 37345133, 2023). "We aim to develop 68Ga-labeled pyridine-based FAP-targeted tracers for cancer imaging with positron emission tomography (PET), and compare their imaging potential with the clinically validated [68Ga]Ga-FAPI-04." (PMID 36986548, 2023). "In this study, we found that FAP expression was positively correlated with the infiltration of cancer associated fibroblasts, macrophages, as well as CSF1R protein in most cancers." (PMID 37166418, 2023). "For cancer immunotherapy, an ideal anti-FAP CAR would be engineered to target FAP expression by fibroblasts while sparing NK cells." (PMID 38196606, 2023). "Cancer therapies specifically targeting FAP are still in their early phases, with several strategies being explored, such as FAP-targeted antibodies and small molecule inhibitors, vaccine therapy, and CAR T-cell therapy (NCT03932565)." (PMID 38102692, 2023). "Clearly, an expansion of the functional roles of FAP-α is necessary to expand our understanding of this important target in cancer and in other diseases." (PMID 36937451, 2023).
cancer (continued). "In the present study, 68Ga-FAPI-RGD, a heterodimeric PET tracer that targets both FAP and integrin αvβ3, was evaluated in 3 healthy volunteers and 22 patients with cancer." (PMID 37142301, 2023). "A series of radiotracers targeting fibroblast activation protein (FAP) with great pharmacokinetics have been developed for cancer diagnosis and therapy." (PMID 36864362, 2023). "Multiple preclinical studies of FAP-targeting immunotherapies in various cancer types have shown potential promise and limited toxicities." (PMID 37333052, 2023). "FAP was found primarily expressed in fibroblasts across these cancers by single-cell sequencing analysis, verified previous findings that FAP behaves as a marker of CAFs." (PMID 37325617, 2023). "FAP-expressing CAFs actively interact with cancer and immune cells and participate in the modification of the extracellular matrix." (PMID 36825204, 2023). "which showed that FAP was significantly overexpressed in multiple cancers compared to matched control tissues." (PMID 37752545, 2023). "We demonstrate that FAP expression is significantly upregulated in most cancer types both in mRNA and protein levels." (PMID 37166418, 2023). "Recent work has highlighted that FAP expression is markedly upregulated in various cancers and has gained interest as a potential small molecule inhibitor." (PMID 37111277, 2023). "Cancer-associated fibroblasts were clearly divided into three clusters, and their marker genes were DCN, FAP and RGS5." (PMID 37963845, 2023). "FAP is highly expressed in stroma of most carcinomas, including PDAC9, and mesothelin is a promising TAA target expressed at high levels in PDAC 24,26." (PMID 37607999, 2023). "Among this subset, 8 out of 13 FAP positive carcinomas displayed high microsatellite instability (MSI-high)." (PMID 37614665, 2023). "The goal of the present work was to develop novel boroPro-based PET imaging agents with superior pharmacokinetics properties and excellent imaging contrast for easy and reliable diagnosis of FAP-overexpressing carcinomas." (PMID 37375746, 2023). "FAP has a restricted normal tissue distribution including normal fibroblasts, but is overexpressed in the reactive stromal fibroblasts of >90% of human epithelial carcinomas (breast, lung, colorectal etc.)." (PMID 37375746, 2023). "FAP has been proposed as one of the primary markers of CAFs being overexpressed in 90% of carcinomas, such as melanoma, colorectal, breast, ovarian, bladder, and lung and with high therapeutic potential." (PMID 37168385, 2023). "FAP is overexpressed in CAFs of 90% epithelial carcinomas, including HCC, and liver background uptake is low on 18F-FAPI PET/CT." (PMID 37899452, 2023). "Differently FAP is overexpressed in the CAFs of 90% of epithelial carcinomas, including primary and metastatic liver cancer." (PMID 37763225, 2023). "Fibroblast activation protein-α (FAP), named after its activating role, is a type II transmembrane serine protease with specific endopeptidase activity that is upregulated in different cancer types." (PMID 36263225, 2022). "IMPLICATIONS FOR PATIENT CARE: This first-in-humans use provides a direction to clinical trials for promising and effective FAP-targeted radiopeptide therapy in various aggressive cancers." (PMID 34168013, 2022). "Strong FAP expression was observed in 50%–100% of cancers from the bile duct, bladder, colon, esophagus, stomach, lung, oropharynx, ovary, and pancreas." (PMID 34740953, 2022). "The influence of GPX4 on cancer prognosis agreed with that of FAP, indicating a significant relationship between FAP and ferroptosis." (PMID 35359436, 2022). "We use TCGA data to analyzed the expression levels of FAP by comparing it in 33 types of cancers vs. adjacent samples." (PMID 35359436, 2022). "In a landmark study using a transgenic mouse expressing the diphtheria toxin receptor under the FAP promoter, depleting FAP+ CAFs by diphtheria toxin administration improved anti-cancer vaccination efficacy." (PMID 36010899, 2022).
cancer (continued). "After the identification of the FAP inhibitor (FAPi) lead molecule UAMC-1110, many FAP-targeting imaging tools based on the same quinoline scaffold were designed for theranostic applications in a variety of cancers." (PMID 35215346, 2022). "FAP showed a prognostic value in many cancers, and a high expression of FAP tended to predict a poor prognosis." (PMID 36387219, 2022). "The first approach toward using FAP as a target in cancer treatment applied the monoclonal antibody sibrotuzumab and was tested in both an unconjugated and a 131I-conjugated format for colorectal cancer." (PMID 34168013, 2022). "Because FAP is overexpressed in many cancers, radiolabeled molecules targeting FAP are studied for their use as pancancer theranostic agents." (PMID 34740953, 2022). "[68 Ga]FAPI-04 is a 68 Ga-labeled small molecular FAP inhibitor that has been evaluated in 28 different human cancers." (PMID 35028820, 2022). "Accordingly, several groups have successfully provided proof-of-concept that alpha therapy targeting FAP in the cancer stroma is effective." (PMID 35719937, 2022). "Fibroblast activation protein (FAP) is strongly overexpressed in the stroma of human cancers, including SFTs, and its quinoline-based FAP inhibitor can be internalized after binding to the FAP enzymatic domain." (PMID 36012988, 2022). "We first surveyed tissue microarrays (TMAs) of 141 patients with 14 cancer types for the presence and degree of FAP expression by immunohistochemistry." (PMID 34740953, 2022). "Fibroblast activation protein (FAP) is a promising target for diagnosis and therapy of numerous malignant tumors." (PMID 34168013, 2022). "Preclinical studies in several cancer types suggest a synergistic effect of FAP targeting and immunotherapy." (PMID 34385340, 2022). "Given its restricted expression profile and functions, FAP is a promising target for the selective delivery of anticancer therapies to tumors of a broad range of cancer indications." (PMID 35608703, 2022). "Previous studies have found that overexpression of FAP facilitates cancer cell proliferation, invasion, and angiogenesis and serves as a novel target for various cancer therapies." (PMID 35911706, 2022). "CAF populations expressing FAP/ITGA11/COL1A1/CCN2 have been shown to be negatively correlated with disease-free survival in this cancer." (PMID 35326670, 2022). "A selective overexpression of FAP in the stroma of epithelial tumors and malignancies of bone and soft tissues contributes to the invasiveness and progression of cancer." (PMID 35471681, 2022). "An increase in mRNA expression of CXCL12, CXCR4, and FAPα was observed in residual cancer tissues after nCRT treatment." (PMID 34976180, 2022). "There was a significant correlation of the CXCL12 levels in plasma membrane expression and CXCR4 and FAPα levels in the cancer cells of LARC after nCRT group (Spearman's Rho: p = 0.001 and p = 0.003)." (PMID 34976180, 2022). "Various strategies to enhance immunity against FAP-expressing cells (i.e., CAFs) and to suppress cancer growth have been explored." (PMID 36010899, 2022). "As a result of these characteristics, FAP poses a promising target for the characterization of cancers." (PMID 36428657, 2022). "FAP is an increasingly recognized CAF marker, and high FAP protein expression in various cancers often indicates an aggressive course." (PMID 35052475, 2022). "In recent years, quinoline-based fibroblast activation protein (FAP) inhibitors (FAPI) have shown promising results in the diagnosis of cancer and several other diseases, making them the hotspot of much productive research." (PMID 35198057, 2022). "IMPLICATIONS FOR PATIENT CARE: Albumin binder conjugation is a promising strategy in the development of FAP-targeted radiopharmaceuticals for treating cancers." (PMID 34593598, 2022).